Y_RNA (Y RNA )
Gene: Miscellaneous RNA gene on chromosome 7 (92,202,243 to 92,202,334, reverse strand). Ensembl gene ENSG00000200769.
Homologues: Orthologues: chimpanzee Y_RNA (99% identical). Paralogues in human: Y_RNA (88% identical), RNY3 (87% identical), Y_RNA (87% identical), Y_RNA (86% identical), RNY3P1 (85% identical), Y_RNA (85% identical), RNY3P16 (84% identical), Y_RNA (84% identical), Y_RNA (83% identical), RNY3P14 (82% identical), RNY3P5 (82% identical), Y_RNA (82% identical), and 90 more.